VIM (vimentin)
Diseases named in the same sentence as VIM in open-access papers (continued):
Sharing a sentence is not in itself a finding about the gene and the disease.
cancer (continued). "On the other hand, vimentin is one of EMT protein markers, which is present in mesenchymal cells and involved in cancer progression." (PMID 36712971, 2022). "We also checked expression of EMT markers, such as E-Cadherin, Krt12, Vimentin, Survivin, Slug, ZEB1 and ZEB2, in the TNBC cancer cells, and found that expression of ZEB1 was positively correlated with expression of SENP1." (PMID 35342335, 2022). "Coculturing RUNX1-silenced HT29 cancer cells with IHH hepatocytes abolished the expression of ARP2/3 and vimentin in the hepatocytes." (PMID 35267627, 2022). "EMT is a phenomenon in which the infiltration capacity is strengthened by showing a decrease in the E-cadherin (CDH1) expression involved in cell adhesion and an increase in vimentin (VIM) expression, which is a mesenchymal marker, in cancer." (PMID 35330413, 2022). "The expression of cancer stem cell markers CD24 and CD44, cytokeratins, and vimentin was investigated by immunofluorescence." (PMID 35563359, 2022). "Conversely, the mesenchymal markers fibronectin, N‐cadherin and vimentin, the EMT‐TFs Snail, Slug, Zeb1 and Zeb2, and the cancer stem cell markers CD44, Sox2 and Id1 were strongly induced by TGFβ and repressed by BMP in 3D cultures." (PMID 35348275, 2022). "Vimentin is one of the main mediators of EMT and metastasis in a variety of cancers and is itself a target of post-transcriptional gene regulation." (PMID 35359446, 2022). "Although the SPARC and VIM genes had higher expression rates in GBM, they were found high in other cancer types." (PMID 35571016, 2022). "In accordance with the functional and mechanistic links between EMT and cancer stemness, the levels of EMT markers such as vimentin, N-cadherin, and AXL were higher in sphere cells." (PMID 35956408, 2022). "In turn, overexpressed AKR1B10 promotes p-ERK1/2, MMP2, and vimentin expression, which mediate activation of the MAPK signaling pathway, thereby enhancing cancer cell proliferation and invasion in vitro and in vivo." (PMID 35563845, 2022). "When tumors promote cancer cell invasion and metastasis through the EMT pathway, CDH1 and Vimentin are often downregulated, while CDH2 is overexpressed." (PMID 35657638, 2022). "After SMAD trimer translocation, E-cadherin diminished, and N-cadherin and Vimentin were enhanced, thus facilitating EMT in cancer." (PMID 36248424, 2022). "We observed the elevated expression of fibronectin, vimentin, MMP-9, and N-cadherin with a parallel reduction in the levels of occludin and E-cadherin in the untreated cells indicating that the tested cancer cells present mesenchymal-like characteristics." (PMID 35883447, 2022). "Treatment with exosomes derived from donor cancer cells increases the expression of HULC and EMT markers, such as vimentin, in recipient cancer cells and promotes invasion and migration." (PMID 35055115, 2022). "Vimentin contributes to the epithelial-to-mesenchymal transition (EMT) and cancer cell mechanics by mediating the cytoskeletal organization and focal adhesion maturation." (PMID 34066763, 2021). "Since epithelial-to-mesenchymal transition (EMT) actively relates to the invasion and metastasis of cancer cells, the expression of EMT markers such as vimentin and E-cadherin in PCa cells following knockdown of UBXN1 and ARRDC4 was characterized." (PMID 34680357, 2021). "Moreover, the expression of plectin, like that of vimentin, is upregulated in different types of carcinoma cells and tumor tissues, and curiously, plectin, has been localized on the extracellular surface of pancreatic ductal adenocarcinoma and other cancer cells." (PMID 34440923, 2021). "Even in the cancer tissues from NSCLS patients, Id1 seems to be significantly related to the vimentin and other EMT-related proteins." (PMID 33936204, 2021).
cancer (continued). "Based on the successful establishment of the NSCLC PDX model, we compared the expressions of vimentin, Ki67, EGFR, and PD-L1 proteins between cancer tissues and PDX models using hematoxylin and eosin staining and immunohistochemical staining." (PMID 33628593, 2021). "Moreover, Ki67, ezrin, and vimentin may serve as potential therapeutic targets in cancer." (PMID 34198671, 2021). "Vimentin is a typical marker of mesenchymal phenotype, which was positively correlated with the levels of OSCAR in 17/20 types of cancer, especially BLCA (r=0.594), COAD (r=0.759), LUSC (r=0.606), and READ (r=0.724)." (PMID 34093786, 2021). "Vimentin is considered as a protein marker of EMT reprogramming, in which cancer cells acquire migratory and invasive phenotypes." (PMID 33757532, 2021). "The genes selected included epithelial (KRT5, CDH1, EpCAM), mensenchymal (VIM, SNAI1, TWIST), stem (ALDH1A1, PROM1), breast specific (ESR1, PALB2) and other genes related to cell cycle or other cancer pathways (CCND1, CTNNB1, Ki67, etc.)." (PMID 34071445, 2021). "We also found strong correlations between MES and ADRN TFs with markers of cancer cell stemness and cancer cell motility including CDH1, CDH2, NANOG, SOX2, TWIST1, VIMENTIN, and Fibronectin across cancers." (PMID 35201514, 2021). "This is the first study to demonstrate that the circ-SIRT1/EIF4A3/N-cadherin/vimentin axis promotes the proliferation and EMT of CRC cells, providing a novel therapeutic target and strategy for the treatment of this cancer." (PMID 34660182, 2021). "Over-expression of vimentin in cancer cells is highly correlated with cancer progression, and EMT would lead to the translocation of vimentin from the intracellular region to the cell surface to become cell surface vimentin (CSV)." (PMID 34055642, 2021). "The immunofluorescence analysis showed that MAs upregulated vimentin expression in all four cell types, whereas the induction of ICAM-1 expression was evident only in cancer cells." (PMID 33921783, 2021). "These include vimentin and/or ICAM-1, whose expression was elevated in MAs-treated cancer and normal cells." (PMID 33921783, 2021). "The loss of E-cadherin expression together with increased expression of N-cadherin and vimentin were recognized as the marker of EMT, and were found in various cancers." (PMID 34889713, 2021). "In cancer cells cultured with each CAF-CM, the mRNA expression of vimentin, which was the EMT marker, was significantly increased, and the mRNA expression of E-cadherin was significantly decreased (P < 0.05)." (PMID 33659044, 2021). "VIM is considered a biomarker of mesenchymal-derived cells and cancer cells undergoing epithelial-mesenchymal transition (EMT) during invasion and metastasis, and promoter methylation of VIM has been documented in CRC." (PMID 33030559, 2021). "Vimentin, an intermediate filament of mesenchymal cells, is upregulated in epithelial-mesenchymal transition (EMT) and has a main role in cancer metastasis." (PMID 35178358, 2021). "EMT biomarkers such as Vimentin, N-cadherin, and MMP9 are overexpressed in cancer and are involved in promoting cancer cells metastasis." (PMID 34458309, 2021). "It has been reported that by combining two mesenchymal markers, vimentin and E-cadherin, EMT statues of many cancer types can be identified." (PMID 34795689, 2021). "Vimentin, HSP-27 and Fibronectin are the three important potential targets in the case of cancer therapy." (PMID 34200663, 2021). "One of the key biomarkers of EMT is vimentin, a type III intermediate filament that is normally expressed in mesenchymal cells but is upregulated during cancer metastasis." (PMID 34638469, 2021). "Vimentin is also known to regulate surface translocation of matrix metalloproteases such as MT1-MMP, which play a key role in conferring cancer cell motility and invasive capability." (PMID 34831127, 2021).
cancer (continued). "As an important intermediate filament family member whose expression was frequently caught in multiple malignant tumors especially TNBC, Vimentin was identified as a potential binding protein of HRD1 with high probability." (PMID 33530981, 2021). "Oncogenes such as c-Myc can induce cellular stiffness and confer invasive potential to cancer cells via HDAC6-dependent deacetylation of α-tubulin and reorganization of the vimentin network." (PMID 34638469, 2021). "In the migrating cancer cells, the YRKLLEGEE motif in the rod sub-domain 2B of vimentin interacts with K14 to support cell migration." (PMID 34638469, 2021). "The majority were localized to cluster lungH1 and expressed lower levels of metastatic cancer cell markers (ALDH3A1, VIM, TCEAL9)." (PMID 34579762, 2021). "Then we separated cancer cells from the metastases of mice lung tissues and detected miR-18b, TCEAL7, E-cadherin, and Vimentin expression in lung metastatic cells." (PMID 34853307, 2021). "Our results revealed that the expression of CK-18 and E-cadherin were downregulated, and the expression of genes related to EMT induction and cancer aggressiveness, including Twist, Snail, SOX2 and Vimentin, were upregulated upon HK2 overexpression." (PMID 34174908, 2021). "Increased vimentin expression has been reported in a low adherent and more metastatic sub population of MDA-MB-231 cancer cells." (PMID 34203746, 2021). "This same study also found that cancer cells with a high rate of CIN displayed mesenchymal cell traits, including increased motility, invasiveness, and vimentin expression." (PMID 33921421, 2021). "First, BK channels modulate cancer cell migration through reduced cell‐cell contact by regulating the expression of EMT related proteins such as E‐cadherin, Vimentin and N‐cadherin." (PMID 34514691, 2021). "Activated vimentin drives EMT and cancer dissemination by orchestrating the focal adhesion complex and cytoskeleton remodeling." (PMID 34830801, 2021). "Western blot analysis showed that E-cadherin was remarkably promoted following CTD treatment, and N-cadherin and vimentin were decreased, which are all markers of the EMT process in cancers." (PMID 33785035, 2021). "According to the canonical conception, TGF-β promotes EMT during cancer cell motility, invasion and metastasis; therefore, the EMT markers such as FN and VIM are induced." (PMID 33917452, 2021). "Recently, disseminating hybrid E/M CSCs that co-express EpCam, Vimentin, and CD24 have been observed in human cancer specimens, thus proving that a hybrid E/M CSC-like state is predictive of metastasis." (PMID 34830900, 2021). "SNAI1-induced EMT in cancer cells promotes a more fibroblast-like appearance and increases the invasive behavior by suppressing CDH1 and β-catenin expression through elevated vimentin expression." (PMID 34455105, 2021). "qRT-PCR was used to examine the mRNA levels of some cancer markers such as cell cycle marker (CDK1), epithelial marker (E-cadherin), and mesenchymal marker (vimentin) in Caco-2 cells treated with SE and ZnO SE." (PMID 34976976, 2021). "To summarize these data in general, we have shown that recombinant vimentin has effects on cell proliferation, adhesion, and migration, and on epithelial cell monolayer permeability in MCF-10a control cells and MCF-7 cancer cells." (PMID 34299089, 2021). "Therefore, during complex EMT events, increased vimentin expression (and its phosphorylated version) may regulate cell migration, cancer invasion and apoptosis evasion through the ITGβ4 transcriptional regulation and associated multiple signalling pathways, highlighted above." (PMID 34638469, 2021). "We showed previously that the upregulation of catulin expression in vitro correlates with the transition of cancer cells from an epithelial to mesenchymal morphology, and the increased expression levels of EMT markers Vimentin and Snail." (PMID 35008571, 2021).
cancer (continued). "EpCAM and vimentin, two prototypic epithelial and mesenchymal markers in EMT and EndoMT, are of particular clinical values in cancer patients." (PMID 34455700, 2021). "In contrast, AS906 and AS914, which derived from carcinomas with sarcomatoid features and formed loose spheroids in culture, expressed ZEB1, SNAI2, CD44, and Vimentin, but negligible levels of EpCAM and E-Cadherin (CDH1)." (PMID 33941777, 2021). "CNTN1 inhibition also increased expression of E-cadherin while reduced N-cadherin and Vimentin, suggesting an inhibition of the EMT process pivotal in cancer metastases." (PMID 32752094, 2020). "Using immunofluorescence analysis, the protein expression of Nestin, Sox2, Vimentin, and GFAP was analyzed in these primary cancer cell lines." (PMID 32742192, 2020). "As expected, CAFs expressed PDGFRβ and FSP1, and cancer cells E‐cadherin and PAX8, whereas both cell types were positive for vimentin and N‐cadherin." (PMID 32115889, 2020). "In addition, studies suggested that HIF-1α might also regulate the invasiveness of cancer cells by altering the expression of intermediate filament (vimentin, keratin), extracellular matrix component (fibronectin), and protease (MMP2 and urokinase plasminogen activator receptor)." (PMID 32211041, 2020). "For example, TAp73 isoforms control cancer cell proliferation, migration and invasion through transactivation of the brain-enriched miRNA gene MIR3158, which targets vimentin." (PMID 33339112, 2020). "We also found that overexpression of PDCD10 increased cancer metastasis by down-regulating CDH1, enhancing VIM expression, and inducing EMT." (PMID 32483426, 2020). "While in our study, the activities of pristimerin to reduce the cellular cytoskeleton of vimentin and F-actin, cellular adhesion of integrin β1, as well as cellular invasion of MMP2, exerted the multiple ways of anti-cancer potential." (PMID 33033518, 2020). "Up-regulated vimentin is strongly related to epidermal-mesenchymal transition (EMT) in epithelial cell cultures, which plays an important role in cancer metastasis." (PMID 32438542, 2020). "Targeting of CARF by Snol-A also caused (i) downregulation of pATR-Chk1 signaling leading to caspase-mediated apoptosis and (ii) inactivation of β-catenin/Vimentin/hnRNPK-mediated EMT signaling resulting in decrease in migration and invasion of cancer cells." (PMID 32286347, 2020). "This analysis showed higher STAMBPL1 expression in the metastatic lesion, along with more vimentin and reduced E-cadherin protein staining, further supporting a role of STAMBPL1 in an aggressive cancer phenotype." (PMID 32636467, 2020). "It has been demonstrated that ZEB2 interacts with the transcription factor Sp1 to activate the expression of mesenchymal genes and vimentin expression, leading to EMT in human cancer cells." (PMID 32149094, 2020). "Vimentin, a cytoplasmic protein comprising intermediate filaments, is known to be upregulated in EMT-induced cancer cells and correlated with cancer progression." (PMID 33266262, 2020). "The AR functions in cell migration and cancer metastasis by regulating its major target genes E-cadherin (CDH1) and vimentin (VIM)." (PMID 32847068, 2020). "Cancer tissues had lower E‐cadherin and higher vimentin, Snail and ZEB‐1 expression than para‐carcinoma tissues suggesting that EMT, along with a down‐regulation of RXRα expression, was promoted in cancer tissues." (PMID 33128348, 2020). "Accordingly, the expression of EMT actors (e.g., vimentin, Twist, Snail, or ZEB1) has been detected in CTCs in animal models and extensively reported in subpopulations of CTCs isolated from cancer patients." (PMID 32152404, 2020). "The differences in cell differentiation and cancer-related genes (AFP, NOTCH1, CSF1, NOTUM, TGFβ, and vimentin genes) implied different biological characteristics between cells cultured in the 3D and 2D models." (PMID 32582546, 2020).
cancer (continued). "Previous publications have demonstrated that VIM is a specific EMT marker and is localized on the surface of various types of cancer cells." (PMID 31981446, 2020). "PKM2 knockdown suppressed cancer cell invasion and migration and inhibited the epithelial-mesenchymal transition (EMT) phenotype by inhibiting E-cadherin and promoting vimentin and N-cadherin expression." (PMID 33376737, 2020). "Statistically, a significant increase of vimentin and FZD10 expression was recorded when HCEC-1CT cells were incubated with exosomes isolated by either the two cancer cell lines, at each investigated incubation time." (PMID 32933173, 2020). "Many factors, including EphA2, Notch4, VE‐cadherin, SLPI, TWIST, VEGF, vimentin and HIF‐1α, are related to the formation of VM in many cancers." (PMID 33118329, 2020). "Epigenetic regulation of vimentin expression has also been shown to play an important role in EMT and cancer progression." (PMID 31940801, 2020). "Mesenchymal markers including Vimentin and N-cadherin are indicators of the EMT and cancer metastasis." (PMID 32857728, 2020). "So far, miR-30c has been reported to be targeted and regulated by the transcription factors including Myc, HMBOX1 and C/EBP alpha with the target of miR-30cincludingMTA1, KRAS, BCL-9,Notchand cancer cell invasion related genes including TWF1, VIM and CCND2." (PMID 32201529, 2020). "Among the five overlapped genes, vimentin and MMP3, which have been widely recognized as key regulators in promoting cancer invasion and metastasis, drew our great attention to postulate that miR-515-3p may exert its suppressive effect on cancer mobility through its regulation on vimentin and MMP3." (PMID 33243974, 2020). "We next compared the expression patterns of VIM (vimentin) and CDH1 (E-cadherin) with those of Sipa1 using qRT-PCR in the cancer cell lines studied herein." (PMID 32193333, 2020). "We next examined the importance of vimentin and MMP3 in the functional role of miR-515-3p in cancer metastasis." (PMID 33243974, 2020). "The expression of E-cadherin, N-cadherin or vimentin in CCA samples was separated into high and low groups according to the median percentage of stained cancer cells." (PMID 33060563, 2020). "Since the EMT process appears to be critical to the metastasis of almost all carcinoma types, including CRC, we investigated the effects of BCKDK on the expression of EMT markers (E-cadherin, Vimentin, and N-cadherin)." (PMID 32238881, 2020). "E-cadherin, N-cadherin and Vimentin are classical markers of epithelial-to-mesenchymal transition (EMT) that play a vital role in invasion and metastasis of carcinomas." (PMID 33317527, 2020). "Vimentin acts as a key factor in the final stage of EMT program and indicates the highly proliferative and invasive state of mesenchymal-like carcinoma cells." (PMID 32934214, 2020). "Previous studies have found that cancer cells activate the AKT/MAPK signaling pathway, which in turn induces the snail pathway, regulating the expression of E-cadherin and vimentin, which can transform normal epithelial cells to interstitial cells." (PMID 30841634, 2019). "We show that the covalent modification of vimentin by ajoene disrupts the vimentin filamentous network that in turn counters the metastatic phenotype of MDA-MB-231 and HeLa cancer cells." (PMID 30894168, 2019). "Both EMT and cancer metastasis are stimulated by an increase in SNAI1, N-cadherin, Zeb1, and vimentin, and a decrease in E-cadherin." (PMID 30736337, 2019). "Genetic knockdown of EHMT2, a histone methyltransferase, reduces cancer cell migration and invasion by regulating the expression of EMT-related markers (E-cadherin, claudin-1, and vimentin)." (PMID 31717460, 2019). "In contrast, the overexpression of UCA1 in DU-145 showed increased level of E-cadherin but decreased level of Vimentin, MMP-9 and N-cadherin (P<0.01), validating the aggressive role of UCA1 in cancer metastases." (PMID 30940776, 2019).